BRAF (B-Raf proto-oncogene, serine/threonine kinase)
Diseases named in the same sentence as BRAF in open-access papers (continued):
Sharing a sentence is not in itself a finding about the gene and the disease.
papillary thyroid carcinoma (continued). "BRAF mutations are implicated in the development of papillary thyroid carcinoma, and have also been identified in Langerhans cell histiocytosis." (PMID 30795755, 2019). "For example, papillary thyroid cancers with BRAF mutations are associated with reduced expression of key genes involved in iodine metabolism, including NIS." (PMID 31200667, 2019). "DNA extracted from 100 thyroid tumors (10 follicular adenomas, 10 follicular cancers, 5 medullary cancers, and 75 papillary thyroid cancer (PTC) were used for detection of BRAF and TERT mutations." (PMID 31810221, 2019). "BRAF mutation in papillary thyroid carcinoma (PTC) is associated with an aggressive phenotype, with varying incidence." (PMID 30694737, 2019). "In patients diagnosed with classic histology papillary thyroid cancer treated from 1973 to 2009, BRAF V600E mutation status was determined on surgical tumor specimens by restriction fragment length polymorphism analysis." (PMID 30552739, 2019). "Iodine supplementation has also been proposed as a determining factor, mainly in the increase of papillary thyroid cancer and the prevalence of BRAF mutations." (PMID 30105053, 2018). "For example, the BRAF V600E mutation is strongly associated with conventional papillary carcinoma, BRAF K601E, with the follicular variant of papillary carcinoma, and PTEN, with follicular carcinoma." (PMID 30340539, 2018). "The aim of the present study was to investigate the association between matrix metalloproteinase-9 (MMP-9) expression with BRAF V600E mutation and clinicopathological features, in Iranian papillary thyroid cancer (PTC) patients." (PMID 30509240, 2018). "Meanwhile, DUSP4/MKP2 overexpression is also associated with the aggressive behavior of BRAF V600E-mutated papillary thyroid cancer." (PMID 30111351, 2018). "This image illustrates a multimodal therapeutic strategy for an iodine-refractory BRAF-mutated metastatic papillary thyroid carcinoma with reversed radioiodine resistance using BRAF inhibitors." (PMID 30337961, 2018). "DUSP5 mRNA levels were 7.9 fold higher in BRAF-mutated papillary thyroid carcinoma (PTC) than in normal adjacent tissue (P = 6.3.10−58) and 1.5 fold higher in RAS-mutated PTC than in normal adjacent tissue (P = 8.10−3)." (PMID 28910386, 2017). "Recent advance of the cancer genetics showed major mutation of papillary thyroid cancer: BRAF V600E accounts for 60%, RAS for 15%, and receptor tyrosine kinase (RTK) for 12%." (PMID 29085335, 2017). "Gene alterations in the MAPK/ERK pathway, e.g. BRAF mutations, have been identified in around 60% of papillary thyroid carcinoma (PTC) and 15–45% of ATC." (PMID 28489587, 2017). "BRAF-mutated papillary thyroid cancers showed lower expression of thyroid-specific genes, which are related to iodine accumulation, than RAS-mutated papillary thyroid cancers." (PMID 29085335, 2017). "Especially, mutations of the TERT promoter, RET, and BRAF are established as major prognostic biomarkers and are associated with clinical aggressiveness of papillary thyroid carcinoma." (PMID 29108240, 2017). "This study is to investigate if any relationship exists between the telomerase reverse transcriptase (TERT) promoter or proto-oncogene BRAF mutation and ultrasound (US) and clinicopathological features of papillary thyroid carcinomas (PTCs)." (PMID 29312581, 2017). "How the BRAF V600E mutation promotes the pathogenesis and aggressiveness of papillary thyroid cancer (PTC) is not completely understood." (PMID 27863429, 2017). "The BRAF V600E mutation is the most common genetic event occurring in papillary thyroid cancer (PTC)." (PMID 29088832, 2017). "The genetic alterations responsible for NIFTP include RAS oncogene alterations, similar to those driving follicular adenoma and follicular carcinoma tumors, in contrast to the BRAF oncogenes mutated in the classic papillary thyroid cancer pathway." (PMID 28280647, 2017).
papillary thyroid carcinoma (continued). "BRAF mutations are closely associated with aggressive clinicopathological characteristics and poorer prognosis in papillary thyroid cancer." (PMID 27600854, 2016). "BRAF mutations occur in approximately 8% of human tumors and are also widespread in papillary thyroid cancer (36–69%)." (PMID 27057371, 2016). "BRAF oncogene mutation occurred in approximately 45% to 70% of patients with papillary thyroid carcinoma and VEGF overexpression is frequently found in tumors that originated in the thyroid." (PMID 27703281, 2016). "The BRAF V600E mutation is commonly observed in papillary thyroid cancer (PTC) and predominantly activates the MAPK pathway." (PMID 27127178, 2016). "BRAF mutation testing which is a powerful molecular marker for papillary thyroid carcinoma, cutaneous malignant melanoma, and hairy cell leukemia is also recommended." (PMID 27127670, 2016). "Accordingly, aggressive treatment should be considered for papillary thyroid cancer patients with BRAF mutation." (PMID 27600854, 2016). "BRAF somatic mutations, the most extensively investigated molecular markers, are the most common genetic alterations in papillary thyroid carcinoma (PTC)." (PMID 27410688, 2016). "MiR-146b expression level was significantly higher in papillary thyroid carcinoma with BRAF mutation and significantly associated with invasive behavior." (PMID 26646588, 2016). "BRAF-V600E and TERTp mutations were recently found cooperatively identifying the most aggressive subset of papillary thyroid cancer with high recurrence rate." (PMID 26452024, 2016). "The BRAF V600E mutation, a highly specific molecular marker for papillary thyroid carcinoma (PTC), well known for its prognostic value, has dubious diagnostic value because of its low sensitivity." (PMID 26020381, 2015). "BRAF mutations have been found in 29-70 % of PTCs and are associated with oncocytic variants of papillary carcinoma." (PMID 25887408, 2015). "About 50% of papillary thyroid carcinomas (PTC) harbor activating mutations in the BRAF gene (mostly BRAFV600E), an effector of MEK that in turn activates the ERK1 and ERK2 mitogen-activated protein kinases (Review)." (PMID 25879531, 2015). "In Korea, where most of the thyroid malignancy is papillary carcinoma and BRAF mutation is highly prevalent, considerable number of BRAF-negative indeterminate thyroid nodules would be FVPTC." (PMID 25648502, 2015). "If we consider only the classical variant of papillary carcinoma, a correlation between BRAF V600E mutation and a histological diagnosis of malignancy was found in 11/12 (92%) of cases." (PMID 26693224, 2015). "By BigDye Terminator sequencing, BRAF mutation was identified in 62 of 168 (36.9%) cases of unifocal papillary thyroid carcinoma and by pyrosequencing, it was identified in 90 of 168 (53.6%)." (PMID 26448939, 2015). "Recently, MIG-6 expression has been linked to BRAF driven carcinogenesis as patients with V600E positive papillary thyroid cancer (PTC) and low MIG-6 expression demonstrated a more aggressive clinical course as compared to those with high MIG-6 levels." (PMID 26065894, 2015). "Whereas 40 % to 70 % of papillary thyroid carcinomas (PTCs) are characterized by a BRAF mutation (BRAFmut), unified biomarkers for the genetically heterogeneous group of BRAF wild type (BRAFwt) PTCs are not established yet." (PMID 25922907, 2015). "In another family, the siblings have the same variant of BRAF D22N, different from the well-known BRAF V600E variant that is highly prevalent in papillary thyroid carcinoma." (PMID 26530882, 2015). "BRAF mutations (substitution of a valine for a glutamic acid (V599E)) have been implicated in the pathogenesis of papillary thyroid cancer and had been reported to be present in up to 50% of the cases." (PMID 25821606, 2015). "The use of BRAF mutational analysis has been described as a promising diagnostic and prognostic indicator of papillary thyroid carcinomas." (PMID 24839549, 2014).
papillary thyroid carcinoma (continued). "The prevalence of the BRAF mutation in papillary thyroid cancer varies from 32% to 90% in the literature, depending on detection methods and histopathological subtypes." (PMID 24559116, 2014). "Mutation in BRAF correlates with advanced stage, lymph node metastasis, extrathyroidal extension, as well as resistance to traditional radioiodine therapy in papillary thyroid cancer." (PMID 24673746, 2014). "Papillary thyroid carcinoma is the most common endocrine gland neoplasm with a high rate of BRAF V600E mutations." (PMID 25349760, 2014). "The aim of the present study was to investigate the prevalence of the BRAF V600E mutation in papillary thyroid carcinoma (PTC) and to determine the correlation between this mutation and indicators of poor prognosis and outcome in patients with PTC." (PMID 24396464, 2014). "In the present study, we set out to examine the viral DNA and protein in papillary thyroid cancer tissues, and to correlate with the status of tumor BRAF mutation." (PMID 24559116, 2014). "This specific genetic mutation leading to excessive activation of the MAPK pathway accounts for 90% of all cancer-related BRAF mutations and is found in about half of all papillary thyroid cancers and one fourth of anaplastic thyroid malignancies." (PMID 24673746, 2014). "Half of the cases with follicular variant of papillary thyroid cancer were positive for BRAF mutation (P = 0.213)." (PMID 24559116, 2014). "The v-raf murine sarcoma viral oncogene homolog B (BRAF) mutation is the most common genetic alteration in papillary thyroid cancer." (PMID 24559116, 2014). "Analysis of cell cycle status in BRAF-wild-type thyroid cells as well as BRAF-mutated papillary thyroid cancer cells after treatment with PLX4032 was performed by directly measuring DNA replication and assessing cell cycle distribution." (PMID 24673746, 2014). "Specifically, mutations causing over-activation of the mitogen-activated protein kinase (MAPK) signaling pathway are found in more than 70% of papillary thyroid cancers and include BRAF oncogene activation, RAS mutations and RET proto-oncogene rearrangement." (PMID 24673746, 2014). "Given that the majority of our patients had classic subtype of papillary thyroid cancer, our positive rate of BRAF mutation (78%) was compatible to that reported by other endocrine surgery centers." (PMID 24559116, 2014). "Abundance of BRAF mutations in papillary thyroid carcinoma puts forward this matter that suppressing the activity of BRAF can help develop new treatment modalities for the disease." (PMID 23815863, 2013). "The BRAF point mutation is the most common genetic event in papillary thyroid carcinoma (PTC), occurring in 29–69% of such tumors." (PMID 24255689, 2013). "Mutation of T to A at 1799 in the exon 15 of the BRAF gene has been reported in 28–69% of papillary thyroid cancer cases, while point mutations of RAS genes are detected in 5–20%." (PMID 24367375, 2013). "Papillary thyroid cancer with poor prognosis is associated with BRAF mutation, whereas concomitantly, lengthy disease-free interval is not." (PMID 24367375, 2013). "BRAF mutation is an important diagnostic and prognostic marker in patients with papillary thyroid carcinoma (PTC)." (PMID 23883275, 2013). "The most relevant example is the consistent finding of mutations in BRAF in cells from papillary thyroid cancer, which is the commonest in pediatrics." (PMID 23165002, 2013). "The average prevalence of BRAF-positive cases in papillary carcinomas (PTC) was 58.6%, while in follicular variants of papillary carcinoma (FVPTC), the average prevalence was 29.6%." (PMID 23946802, 2013). "The BRAF V600E mutation is usually associated with higher malignancy and aggressiveness in papillary thyroid carcinomas and in most cases with typical ultrasound features of thyroid malignancy." (PMID 23657056, 2013).
papillary thyroid carcinoma (continued). "In thyroid, BRAF V600E mutation is restricted to malignant tumors, and is associated with papillary thyroid cancer (PTC), and PTC-derived poorly-differentiated and anaplastic carcinoma." (PMID 24252159, 2013). "A single hotspot mutation at nucleotide 1799 of BRAF gene has been identified as the most common genetic event in papillary thyroid carcinoma (PTC) with a prevalence of 29–83%." (PMID 23883275, 2013). "For example, the BRAF point mutation (T1799A) occurs in 45% of papillary thyroid carcinomas and is associated with poor clinical outcome, but its high frequency limits its usefulness to address clonality." (PMID 22776144, 2012). "Altogether, it seems that more studies with larger sample size are required to determine the significance of BRAF-V600E mutation effect on papillary thyroid carcinoma patient survival." (PMID 23056577, 2012). "BRAF mutation in papillary thyroid cancer was reported to be a risk factor for worse survival in two studies." (PMID 23056577, 2012). "Summary of studies that reported the status of BRAF mutation in papillary thyroid carcinoma with information on patient survival." (PMID 23056577, 2012). "We also reviewed another 10 independent studies on papillary thyroid carcinoma in which BRAF mutation is prevalent." (PMID 23056577, 2012). "Activating BRAF mutations in papillary thyroid carcinomas have been linked to aberrant methylation of several tumor-suppressor genes, including TIMP3, SLC5A8, DAPK and RARβ2." (PMID 22654559, 2011). "BRAF mutations are the most common somatic mutations in papillary thyroid cancer and are possibly one of the most significant genetic mutation findings in thyroid cancer research." (PMID 24281099, 2010). "In 2005, a DNA microarray analysis on papillary thyroid cancer identified genetic signatures that distinctly correlate with mutations in BRAF, RAS, and RET/PTC papillary thyroid cancers." (PMID 24281099, 2010). "This was followed by the discovery of BRAF mutations, first in melanoma, then in papillary thyroid cancer in 2003." (PMID 24281099, 2010). "In one report, BRAF mutations were found in 44 percent of 500 patients with papillary thyroid cancer." (PMID 21048836, 2010). "In normal thyrocytes cyclin D3 is the predominant D-type cyclin, but in papillary carcinoma cells with BRAF mutation cyclin D3-CDK4 activation is lost." (PMID 19878585, 2009). "In papillary thyroid carcinomas, BRAF mutations, RET/PTC rearrangements, and RAS mutations are mostly mutually exclusive." (PMID 19878585, 2009). "We, and others, have reported a high prevalence of BRAF point mutations (BRAFV600E) in papillary thyroid carcinomas (30% to 69%) and in anaplastic thyroid carcinomas (10% to 35%)." (PMID 19878585, 2009). "Recently, a point mutation in the BRAF gene leading to a V600E substitution has been identified as the most common genetic change in papillary thyroid carcinoma (PTC) occurring in 29–69% of cases." (PMID 17355635, 2007). "Activating mutations in the gene encoding BRAF are the most commonly identified oncogenic abnormalities in papillary thyroid cancer." (PMID 17179987, 2007). "Among these studies, some reported that the BRAF mutation is found frequently only in anaplastic carcinomas with a papillary carcinoma component, although these studies have examined only four or five cases." (PMID 17453004, 2007). "Recently, a somatic point mutation in the BRAF gene has been identified as the most common genetic event in papillary thyroid carcinoma." (PMID 17453004, 2007). "Recently, a mutation in the BRAF gene has been reported to be the most common genetic event in papillary thyroid carcinoma (PTC)." (PMID 16606457, 2006). "Atypical cells suggestive of papillary thyroid carcinoma; BRAF V600E mutation confirmed." (PMID 41559985, 2026).
papillary thyroid carcinoma (continued). "A previous study reported that BRAF V600E mutation is associated with aggressive disease and must be investigated in patients with small papillary thyroid carcinoma (< 1.5 cm) or papillary microcarcinoma (< 1 cm) to help identify high‐risk groups and initiate ideal treatment." (PMID 40085528, 2025). "This study aims to develop an integrated model that combines radiomics, deep learning features, and clinical and ultrasound characteristics for predicting BRAF V600E mutations in patients with papillary thyroid carcinoma (PTC) combined with Hashimoto’s thyroiditis (HT)." (PMID 40900897, 2025). "The tumor‐cell‐origin and molecular pathogenesis remain unclear, although the presence of BRAF mutations in some cases suggest it may evolve from papillary thyroid carcinoma (PTC)." (PMID 40600748, 2025). "Moreover, it is effective for other tumors harboring BRAF V600E mutations, including papillary thyroid cancer, hairy-cell leukemia, and NSCLC." (PMID 40040723, 2025). "The BRAF V600E mutation, a genetic alteration involving a valine-to-glutamate substitution at position 600 of the BRAF gene, is particularly noteworthy due to its strong association with papillary thyroid carcinoma (PTC)." (PMID 40970023, 2025). "Excess iodine may also contribute to papillary thyroid carcinoma (PTC) through increased BRAF mutations." (PMID 40241991, 2025). "We speculate that in this cohort of young patients with papillary thyroid carcinoma, the genetic drivers that result in distant metastasis may be other genes that are mutually exclusive with the BRAF V600E mutation." (PMID 41306438, 2025). "Additionally, mutations in the BRAF gene are linked to papillary thyroid carcinoma (PTC) but can also occur in ATC." (PMID 39767735, 2024). "Papillary thyroid carcinoma with associated BRAF-mutation embedded in an area of fibromatosis which harbors CTNNB1 mutation at the molecular level and nuclear localization of β-catenin makes up the latter tumor, which is remarkable in that it has two distinct components." (PMID 38737660, 2024). "BRAF detection under fine-needle aspiration (FNA) significantly improves the accuracy of papillary thyroid cancer diagnosis, and BRAF mutations correlate closely with larger tumor size, extrathyroidal invasion, multifocality, lymph node metastasis, and advanced staging." (PMID 39363900, 2024). "A point mutation in BRAF is the most common genetic alteration in papillary thyroid cancers." (PMID 36980552, 2023). "Moreover, obesity is significantly associated with several adverse histological characteristics of papillary thyroid cancer at diagnosis, including larger tumor size, multifocality, extrathyroidal extension, lymph nodal involvement, and BRAF mutation." (PMID 37656509, 2023). "However, only a positive BRAF V600E outcome is considered valid, as the majority of follicular variant of papillary thyroid carcinoma (FVPTC) cases are BRAF V600E-negative." (PMID 37623043, 2023). "Both papillary thyroid carcinoma cases harbored BRAF V600E variants." (PMID 36125633, 2023). "Papillary thyroid carcinoma could harbour BRAF mutations, RET/PTC rearrangements, and RAS mutations." (PMID 35328664, 2022). "Lastly, papillary thyroid cancer is related to BRAF V600 mutation." (PMID 36497443, 2022). "Besides, they found a significant association between PD-L1 expression in papillary thyroid carcinomas in terms of underlying chronic lymphocytic thyroiditis and BRAF V600E mutation status." (PMID 34580845, 2022). "The BRAF V600E mutation is an important genetic event in papillary thyroid cancer (PTC)." (PMID 35755312, 2022). "BRAF mutations have been shown to be in about 45% papillary thyroid cancer cases." (PMID 36743179, 2022). "In addition, the BRAF V600E mutation is closely related to recurrence of papillary carcinomas and patient death." (PMID 35356255, 2022).